VIM (vimentin)
Diseases named in the same sentence as VIM in open-access papers (continued):
Sharing a sentence is not in itself a finding about the gene and the disease.
chronic pancreatitis (5 papers, 2006 to 2025). A chronic inflammatory process causing damage and fibrosis of the pancreatic parenchyma. "Many of the upregulated genes in vimentin-expressing α-cells in chronic pancreatitis are associated with motility and proliferation in epithelial cancer cells expressing mesenchymal markers." (PMID 39836539, 2025). "In cells from donors with chronic pancreatitis, there was a limited set of 22 differentially expressed genes in vimentin-positive α-cells, likely due to the limited scale of the dataset." (PMID 39836539, 2025). "Single-cell analysis of dissociated pancreatic cells from nine living donors with chronic pancreatitis confirmed vimentin gene expression in pancreatic stellate, immune, endothelial and acinar cells." (PMID 39836539, 2025). "Additionally, vimentin expression was low in all organoid lines, except for the chronic pancreatitis and the pseudocyst samples." (PMID 32492856, 2020). "Single-cell RNA-sequencing analysis of isolated islets from non-diabetic donors and donors with chronic pancreatitis confirmed the presence of vimentin-positive and vimentin-negative α-cells." (PMID 39836539, 2025). "One out of 18 (5.6%) chronic pancreatitis patients and none of the noncancer controls exhibited reactivity against the antigenic vimentin isoform." (PMID 18769604, 2006). "Only one of 18 chronic pancreatitis patients and none of the healthy controls exhibited reactivity against this vimentin isoform." (PMID 18769604, 2006). "We further validated our finding of a sub-population of vimentin-expressing α-cells in donors with and without overt fibrotic exocrine pathology by interrogating single-cell RNA-seq databases derived from dissociated islets from normal donors and donors with chronic pancreatitis." (PMID 39836539, 2025).
dementia (5 papers, 2012 to 2026). Loss of intellectual abilities interfering with an individual's social and occupational functions. "However, we could confirm the earlier reported correlation of an increase in GFAP and vimentin in grey matter with increasing age and the association of α-synuclein pathology in the frontal cortex with LB-related dementia." (PMID 22577599, 2012). "Seventeen proteins had more than a 50% difference between subjects with dementia and controls, including VIM (2.2 fold increase), NTproBNP (2.2 fold increase), CHIT1 (2.2 fold increase), NEFL (1.7 fold increase), ENPP7 (1.6 fold decrease), and FCGR2A (1.5 fold decrease)." (PMID 37175824, 2023). "We hypothesized that reactive astrocytes in frontal cortical areas of PD brains are associated with the occurrence of dementia, and that this is reflected in GFAP and vimentin levels in the CSF." (PMID 22577599, 2012). "Complementarily to these data, we have found differential patterns of astrocytes implication in dementia using additional markers such as AQP4, GS1, GLAST1, and for ECs such as Lectin UEA, vimentin, PECAM1 and CLDN5." (PMID 34025357, 2021). "Retinal GFAP+ and vimentin+ macrogliosis and IBA1+ microgliosis findings suggest that glial activation and process hypertrophy emerge early along the AD continuum (in MCI due to AD), followed by overt glial proliferation in established AD dementia." (PMID 41571675, 2026). "We now describe that vimentin levels in CSF show the same lack of correlations, making it equally unsuitable as a biomarker for PD or dementia in PD." (PMID 22577599, 2012). "The levels of GFAP and vimentin in CSF did not correlate to the extent of astrogliosis or dementia." (PMID 22577599, 2012). "Thus, we determined whether cortical astrogliosis occurs in PD, whether it is related to dementia, and whether this is reflected by the presence of glial fibrillary acidic protein (GFAP) and vimentin in cerebrospinal fluid (CSF)." (PMID 22577599, 2012). "Therefore, astrogliosis, as demonstrated by GFAP levels and the number of vimentin-positive astrocytes, does not seem to contribute to the frontal-type dementia in PDD and DLB." (PMID 22577599, 2012). "Furthermore, we showed that the presence of GFAP or vimentin in CSF could not be used as an indicator of astrogliosis or dementia." (PMID 22577599, 2012).
desmoid tumor (5 papers, 2019 to 2025). A desmoid tumor (DT) is a benign, locally invasive soft tissue tumor associated with a high recurrence rate but with no metastatic potential. "Immunohistochemistry can assist in the histologic diagnosis of desmoid tumors, as spindle cells typically show positive staining for vimentin, smooth muscle actin, and nuclear beta-catenin, while generally being negative for desmin, cytokeratins, and S-100." (PMID 40349498, 2025). "Desmoid tumor (DT) is a rare neoplasm with high local recurrence rates, composed of fibroblastic cells that are characterized by the expression of key molecules, including the intermediate filament vimentin, cyclooxygenase-2 (COX-2), and nuclear β-catenin, and lack of epithelial markers." (PMID 34595102, 2021). "Microscopically, the tumor was composed of fibroblast, myofibroblast, and infiltrating the inflammatory cell and diagnosed as desmoid tumor by immunostaining (desmin+/−, β-catenin+, CD117−, vimentin+)." (PMID 30820780, 2019).
endometrioid tumor (5 papers, 2012 to 2025). A benign, borderline, or malignant epithelial tumor of the female reproductive system characterized by the presence of glands and/or cysts lined by neoplastic cells that resemble endometrial cells. "Analysis of DE genes between the endometrioid and serous tumors identified fibrosis and collagen deposition as being upregulated in HGSOC, whereas vimentin, a marker of cell invasion, is high in endometrioid tumors." (PMID 40642792, 2025). "Patients with complete loss of vimentin expression in epithelial cells had significantly worse recurrence-free survival compared to patients with vimentin positive tumors in the FIGO I endometrioid tumors (Log rank p < 0.001)." (PMID 37146405, 2023). "The PMCs located near cancer cells in the tumors from patients with HGSOC displayed lower expression of E-cadherin and higher expression of vimentin than the PMCs from patients with endometrioid tumors." (PMID 31086083, 2019). "In the PMCs from the patients with HGSOC, the expression of E-cadherin was decreased and the expression of vimentin was increased compared with the PMCs from the patients with endometrioid tumors." (PMID 31086083, 2019). "Our data is in line with previous reports describing an association between loss of vimentin expression and non-endometrioid tumors, higher FIGO stage, higher tumor grade and worse patient outcome and we here add important information on vimentin in low-stage tumors." (PMID 37146405, 2023).
epithelioid mesothelioma (5 papers, 2017 to 2025). "A diagnosis of epithelioid mesothelioma was made via histopathology and confirmed with immunohistochemistry; it showed positive antibodies against cytokeratin (CK) and vimentin." (PMID 36230301, 2022). "Epithelioid mesothelioma is known to express elevated levels of Claudin-15 and other epithelial markers, whereas non-epithelioid tumors tend to exhibit mesenchymal features such as Vimentin expression." (PMID 41463232, 2025). "Similarly, calretinin and vimentin levels were high in adenocarcinoma relative to their levels in epithelioid mesothelioma." (PMID 35883451, 2022). "In particular the authors evidenced an altered expression of nuclear lamin and related filament proteins such as Vimentin and Desmin suggesting their ability to distinguish epithelioid mesothelioma from other lung malignancies with good values of sensibility and specificity." (PMID 28348450, 2017). "But CK5/6 negative and VIM positive can still discriminate its sarcomatoid identity from the epithelioid mesothelioma." (PMID 34789172, 2021).
fibromatosis (5 papers, 2006 to 2025). A poorly circumscribed neoplasm arising from the soft tissues. "For example, aggressive fibromatosis (a fibroblastic/myofibroblastic tumor) is characterized by diffuse cytoplasmic and nuclear β-catenin positivity along with vimentin and Ki-67 expression." (PMID 40746605, 2025). "The diagnosis of fibromatosis in this work was based on positivity of the spindle cells for vimentin and SMA, a finding described in other studies." (PMID 16859566, 2006). "Regarding to immunohistochemistry (IHC), positive results of Vimentin, β-catenin nuclear staining, and smooth muscle actin (SMA) cytoplasmic staining can be detected in fibromatosis cells whereas staining of S-100, CD34, CKs, and p63 are usually negative." (PMID 40008005, 2025).
gastric tumors (5 papers, 2014 to 2024). "This situation observed for AGS and MKN-45 cells are consistent with the high cell motility and EMT-induction profile defined by the aberrant nuclear vimentin distribution that has been described for both cell lines during a high-throughput analysis of gastric tumors for drug screening." (PMID 34452195, 2021). "In excised human gastric tumors, expression of EGFL7 was positively correlated with expression levels of the mesenchymal marker vimentin and the EMT-associated transcription repressor Snail, and negatively correlated with expression of the epithelial cell marker E-cadherin." (PMID 24945379, 2014). "Based on a correlation with vimentin expression, cell lines having dual CIS/ETP sensitivity are considered to be an EMT subtype (i.e., vimentin+), into which 15% of gastric tumors are classified." (PMID 39461475, 2024). "To further understand the interplay between LGSN and vimentin expression, we found that VIM expression was consistently and significantly up-regulated with LGSN expression in gastric tumor tissues from dataset GSE29272." (PMID 37612301, 2023). "Meanwhile, mRNA levels of NF-kB downstream metastasis-related genes including Vimentin, MMP-2, MMP-9, VEGF, ICAM-1 and VCAM-1 were significantly enhanced in the primary gastric tumors." (PMID 30728051, 2019).
glomus tumor (5 papers, 2015 to 2025). A rare benign or malignant mesenchymal neoplasm arising from cells that resemble the modified smooth muscle cells of the glomus body. "Our findings reinforce the characteristic IHC profile observed in glomus tumors, marked by positive staining for vimentin, SMA, actin, and desmin, which underscore the tumor's smooth muscle and mesenchymal origins." (PMID 39776317, 2025). "Histopathological examination postresection confirmed glomus tumor morphology, with immunohistochemical evidence of smooth muscle actin, H-caldesmon, and vimentin positivity." (PMID 40441262, 2025). "Previous studies revealed that glomus tumors showed positivity for MSA (HHF35) in 18 out of 19 cases, Calponin in 4 out of 5 cases, and vimentin in 12 out of 12 cases." (PMID 30253798, 2018). "Solitary fibrous tumors consist of spindle cells and they are positive for vimentin and CD34 in contrast with glomus tumors." (PMID 26442165, 2015).
hemangioma (5 papers, 2014 to 2024). A benign vascular lesion characterized by the formation of capillary-sized or cavernous vascular channels. "The mesenchymal cell marker, vimentin, was strongly detected in both endothelial cells of the hemangioma and fibroblasts in the PG portion." (PMID 24934284, 2014). "Regarding immunostaining features, the endothelial cell markers, CD34 and CD31, and the mesenchymal cell marker, vimentin, were strongly detected, but cell proliferation marker, Ki-67, was negatively expressed in the endothelial cells of the hemangioma portion." (PMID 24934284, 2014). "The mesenchymal cell marker, vimentin, was strongly detected in both hemangioma and PG portions." (PMID 24934284, 2014). "Hemangiomas show positivity for CD34, CD31, vimentin, and smooth muscle actin." (PMID 39130892, 2024). "Histologically, hemangioma distributed throughout the organ parenchyma and filled with endothelial cells expressing vimentin, factor VIII, and CD 31, but not CD8." (PMID 26166115, 2015).
Hydrocephalus (5 papers, 2013 to 2023). Hydrocephalus is an active distension of the ventricular system of the brain resulting from inadequate passage of CSF from its point of production within the cerebral ventricles to its point of absorption into the systemic circulation. "When comparing obstructive hydrocephalus to controls, only vimentin (VIM) was found to show a higher abundance in controls." (PMID 37857909, 2023). "When stained with a marker for radial glia and migrating neuroblast, the TMEM67 mutant with hydrocephalus displayed an increase of radial distribution of vimentin+ and DCX+ cells in the cerebral cortex as compared to the wild type animals." (PMID 27243144, 2016). "In hydrocephalus vimentin-positive cells increase around disrupted areas of ependyma suggesting that reactive microglia and proliferating immature glial cells are associated with areas of ependymal cell loss." (PMID 24351234, 2013). "This trend contrasted with the overexpression of proteins implicated in metabolism and in the astrocyte reaction, as expected for hydrocephalus according to the literature, such as GFAP and vimentin and the NG2 antigen, the latter present in OPCs." (PMID 34215285, 2021). "It is likely that cells of type B, which have been shown to express GFAP without vimentin expression and type A neuroprogenitor cells, can also be affected after the induction of hydrocephalus because their proliferation was found to decrease." (PMID 35193620, 2022).
lupus nephritis (5 papers, 2018 to 2025). Glomerulonephritis in the context of systemic lupus erythematosus. "In human lupus nephritis, tubulointerstitial inflammation (TII) is associated with in situ expansion of B cells expressing anti-vimentin antibodies (AVAs)." (PMID 33329582, 2020). "We observed that VIM (vimentin) and AQP1 (aquaporin-1) were consistently significant across all three conditions, with meta-p values of 9.03e-141, 0, and 1.14e-121 for VIM, and 0, 1.79e-193, and 8.43e-14 for AQP1 in lupus nephritis, CKD, and control samples, respectively." (PMID 39974940, 2025).
malignant glioma (5 papers, 2006 to 2021). A grade III or grade IV glioma arising from the central nervous system. "EMT, as a key factor of malignant glioma invasion enhancement, can be characterized by an increase in the expression of biomarkers, such as CDH2, VIM, FN1, SNAI1, SNAI2, ACTA2, and so on." (PMID 34034744, 2021). "The results showed that the expression patterns of both VIM and TGF-β were very similar to the expression levels of FN during these distinct progressions of malignant gliomas." (PMID 33917452, 2021). "In contrast, an incomplete co-localization of nestin with intermediate filament bundles containing other intermediate filament proteins (vimentin, GFAP, neurofilament) has been detected in the cell lines derived from PNETs and malignant gliomas." (PMID 16457706, 2006). "Finally, the expression of AEG-1 changes the most compared with the expression of N-cadherin and vimentin during EMT in U251 and U87 malignant glioma cells." (PMID 26909607, 2016).
mucinous tumor (5 papers, 2006 to 2025). "PR and vimentin negativity are helpful in predicting mucinous tumors with high sensitivity and specificity." (PMID 41425725, 2025). "It has been found that ER (clone CC4–5) staining was more dependent on the site of origin, being more common in endometrial than endocervical carcinoma, whereas vimentin positivity is more dependent on the pattern of differentiation, being more common in endometrioid than mucinous neoplasms." (PMID 16409624, 2006). "ER, PR, paired box 8 (PAX8), vimentin, and CA125 positivity support OEC, whereas mucinous tumors show opposite staining profiles." (PMID 41425725, 2025). "Lower average expression of E-cadherin and higher average expression of Vimentin were detected in non-mucinous vs. mucinous tumors." (PMID 39061649, 2024). "More non-mucinous tumors were vimentin-positive tumors than mucinous (22.6% vs.16.9%), and the average Vimentin score was higher in non-mucinous vs. mucinous tumors (0.85 ± 1.73 vs. 0.62 ± 1.47)." (PMID 39061649, 2024).
myoepithelioma (5 papers, 2006 to 2017). "Usually, a combination of a keratin in conjunction with the detection of S100, vimentin, and/or a myogenic marker is required for confirmation of the diagnosis of a myoepithelioma." (PMID 28577557, 2017). "The combination of SMA, GFAP, S-100, and vimentin positive cells in these lesions aids in the diagnosis of malignant myoepithelioma." (PMID 23642050, 2013). "Myoepithelial tumors are characteristically positive for myoepithelial markers including vimentin, cytokeratin, SMA, S100 and GFAP." (PMID 23642050, 2013). "It is suggested that the immunohistochemical expression of vimentin may indicate that myoepithelial cells in tumors such as myoepitheliomas do not reach complete differentiation." (PMID 22152025, 2011). "Almost all cases of myoepithelioma are strongly positive for Calponin, S-100 protein and the tumor cells also display varying degrees of immunoreactivity for cytokeratins, Glial fibrillary acidic protein (GFAP), myosin, actin, vimentin and carcinoembryonic antigen (CEA)." (PMID 18620583, 2008).
nodular fasciitis (5 papers, 2011 to 2025). A self-limiting, rapidly growing, non-encapsulated benign neoplasm that arises from the soft tissues. "Tendon sheath fibroma should also be distinguished from nodular fasciitis, because tendon sheath fibromas share most of the immunohistochemical markers with nodular fasciitis, such as positive vimentin, smooth muscle actin and negative desmin." (PMID 30611237, 2019). "However, the immunohistochemistry for both nodular fasciitis and JFO may show positivity for vimentin, smooth muscle actin (SMA), and desmin." (PMID 39712824, 2024).
pancreatic neuroendocrine tumor (5 papers, 2009 to 2024). Pancreatic endocrine tumor, also known as pancreatic neuroendocrine tumor (PNET), describes a group of endocrine tumors originating in the pancreas that are usually indolent and benign, but may have the potential to be malignant. "Cytologic analysis is diagnostic in 75% of cases with positive vimentin, CD10, and beta-catenin stains differentiating SPTP from pancreatic neuroendocrine tumors." (PMID 27994898, 2016).
paraganglioma (5 papers, 2012 to 2022). A benign or malignant neoplasm arising from paraganglia located along the sympathetic or parasympathetic nerves. "Paragangliomas co-express vimentin, chromogranin A and synaptophysin but lack cytokeratins and calcitonin." (PMID 35805976, 2022). "In our experience, the expression of vimentin in paraganglioma is more marked, extensive and homogeneous than in benign parathyroid disease." (PMID 35805976, 2022). "Apart from central necrosis, vascular and lymphatic invasion and mitotic abnormalities; chromogranin A, vimentin, S-100, synaptophysin can be used in the immunohistochemical analysis of paragangliomas and indicate the true nature of the tumour." (PMID 29255564, 2017). "Chromogranin A and synaptophysin are the most common neuropeptides synthesized in endocrine cells and can be used for immunohistochemical analysis of paragangliomas along with other protein markers such as neuron specific enolase and vimentin." (PMID 23537060, 2013). "Studies have shown that most paragangliomas are S100 positive, synaptophysin (+), pheochromogranin(+), vimentin(+), and AE1 + AE3 negative." (PMID 36581844, 2022). "Clear cell RCCs are frequently immunoreactive with antibodies to CK8/18,vimentin, and CD10; this reactivity is not seen in paragangliomas." (PMID 22741527, 2012).
prostate adenocarcinoma (5 papers, 2011 to 2018). "As has been previously reported for breast and prostatic adenocarcinomas, we found a correlation between vimentin expression and histological differentiation." (PMID 21448168, 2011). "Silybin, at 0.5 and 1% (w/w), has been reported to significantly upregulate E-cadherin and decrease the expression of the EMT markers, vimentin and MMP-2, in transgenic mice with prostate adenocarcinomas." (PMID 29875662, 2018).